H2AC12 (H2A clustered histone 12)
Description:
Core component of nucleosome. Nucleosomes wrap and compact DNA into chromatin, limiting DNA accessibility to the cellular machineries which require DNA as a template. Histones thereby play a central role in transcription regulation, DNA repair, DNA replication and chromosomal stability. DNA accessibility is regulated via a complex set of post-translational modifications of histones, also called histone code, and nucleosome remodeling.
Synonyms: HIST1H2AH; H2AFALii; dJ86C11.1; H2A/S; H2AH
Tractability: PROTAC: UniProt records ubiquitination sites on it; ubiquitination databases record sites on it.
Gene: Protein-coding gene on chromosome 6 (27,147,106 to 27,147,562, forward strand). Ensembl gene ENSG00000274997.
Subcellular location: Nucleus; Chromosome
Subcellular location (Human Protein Atlas): Nucleoplasm
Pathways (Reactome):
Chromatin organization: HATs acetylate histones; HDACs deacetylate histones; RMTs methylate histone arginines
Disease: Dengue Virus-Host Interactions; HCMV Early Events; HCMV Late Events
Metabolism of proteins: Metalloprotease DUBs; UCH proteinases; Ub-specific processing proteases
Gene Ontology:
Molecular function: structural constituent of chromatin; DNA binding; protein heterodimerization activity
Biological process: heterochromatin formation
Cellular component: extracellular exosome; nucleoplasm; nucleosome; chromosome; nucleus
Genetic constraint (gnomAD): Loss-of-function variants: 9 observed, 6.44 expected, observed/expected ratio (o/e) 1.4, 90% interval 0.81 to 1.91. That is too few expected variants to judge how well the gene tolerates losing a copy. Missense variants: 232 observed, 184.48 expected, observed/expected ratio (o/e) 1.26, 90% interval 1.13 to 1.4. Synonymous variants: 158 observed, 81.65 expected, observed/expected ratio (o/e) 1.94, 90% interval 1.67 to 1.99.
Homologues: Orthologues: chimpanzee H2AC12 (100% identical), dog H2AC14 (100% identical), guinea pig H2AC12 (100% identical), macaque H2AC12 (100% identical), pig H2AC12 (100% identical), Drosophila melanogaster His2A:CG31618 (87% identical), Drosophila melanogaster His2A:CG33808 (87% identical), Drosophila melanogaster His2A:CG33814 (87% identical), Drosophila melanogaster His2A:CG33817 (87% identical), Drosophila melanogaster His2A:CG33820 (87% identical), Drosophila melanogaster His2A:CG33823 (87% identical), Drosophila melanogaster His2A:CG33826 (87% identical), and 13 more. Paralogues in human: H2AC11 (100% identical), H2AC13 (100% identical), H2AC15 (100% identical), H2AC16 (100% identical), H2AC17 (100% identical), H2AC14 (99% identical), H2AC7 (99% identical), H2AC18 (98% identical), H2AC19 (98% identical), H2AC4 (98% identical), H2AC6 (98% identical), H2AC8 (98% identical), and 15 more.
Diseases named in the same sentence as H2AC12 in open-access papers:
H2AC12 is named in the same sentence as 5 diseases in open-access papers, as found by Europe PMC text mining. Sharing a sentence is not in itself a finding about the gene and the disease. The quoted sentences say what the papers report.
tumor (1 paper, 2022). "However, the roles of H2AC12 and H2AC21 genes in tumors have not been explored so far; therefore, the mechanisms of these genes in tumor development can be further investigated in the future." (PMID 36553511, 2022).
H2AC12 also shares sentences with these, for which no sentence is quoted: esophageal squamous cell carcinoma (1 paper); hepatocellular carcinoma (1); liver fibrosis (1); systemic lupus erythematosus (1).